TTN (titin)
Diseases named in the same sentence as TTN in open-access papers (continued):
Sharing a sentence is not in itself a finding about the gene and the disease.
heart disease (48 papers, 2013 to 2025). "Previous research has shown that mutations in the TTN gene can compromise the structural integrity and mechanical properties of cardiac muscle fibers and are a common cause of heart diseases, including DCM, HCM, and HF." (PMID 41214391, 2025). "This study described TTN gene variants in Ecuadorian patients with hereditary cardiac diseases, integrating genetic ancestry to improve variant interpretation in an underrepresented population." (PMID 41465321, 2025). "This suggests that TTNtv can modify cardiac morphology in ischaemic heart disease, already the largest cause of left ventricular systolic dysfunction globally, and builds on prior data highlighting the broader role of titin in HF." (PMID 37702310, 2024). "The titin missense variant A178D was identified as the most likely cause of cardiac disease in a family affected by the uncommon autosomal dominant left ventricular non-compaction (LVNC) and dilated cardiomyopathy (DCM)." (PMID 35846001, 2022). "TTN is the largest protein in human, and genetic mutation of TTN was associated hereditary heart diseases." (PMID 36118521, 2022). "The isoform of titin varies with development and isoform variation causes the alteration of cardiac stiffness in the presence of heart diseases." (PMID 36176770, 2022). "Mutations or altered expression of RBM20 can lead to the shift in the expression pattern of titin transcript variants, which are associated with cardiac diseases, including DCM." (PMID 32276354, 2020). "Mutations in titin, MyBP-C and myosin give rise to many forms of heart disease and between them appear to be associated with a majority of HCM cases." (PMID 32619437, 2020). "TTN is the most relevant gene regulated by RBM20 and truncating variants in titin are major determinants of heart disease, accounting for ~30% of DCM." (PMID 32276354, 2020). "In this review, we will discuss the genetics of titin with respect to cardiac disease and how vertebrate animal and cellular models provide insight into the patho-mechanisms related to titin variants." (PMID 31147888, 2019). "RNA binding motif 20 (RBM20) is a key regulator of pre-mRNA splicing of titin and other genes that are associated with cardiac diseases." (PMID 31614708, 2019). "The RBM20 associated heart disease is mainly based on the mis-splicing of pivotal cardiac genes, among which titin is recognized as a major human disease gene." (PMID 29304022, 2018). "Several missense single-nucleotide polymorphisms (mSNPs) in titin have also been associated with heart disease." (PMID 27683155, 2016). "Thus, this study describes genetic variants in the TTN gene of Ecuadorian patients with heart disease, incorporating analysis of individual ancestral components." (PMID 41465321, 2025). "Nevertheless, using a combination of genome-wide linkage and next generation sequencing, we identified the titin missense variant A178D as the most likely cause of cardiac disease in a family affected by autosomal dominant left ventricular non-compaction (LVNC) and DCM." (PMID 33637999, 2021). "The altered ratio between the titin isoforms is associated with cardiac diseases, including DCM." (PMID 32276354, 2020). "The result points to a high potential of titin mSNPs for causing cardiac disease." (PMID 27683155, 2016). "TTN variants have been shown to cause the following cardiac diseases: DCM, RCM, HCM, and ARVC." (PMID 27493940, 2016). "The interaction between deregulated RBM20 and TTN represents a potential mechanism of cardiac disease)." (PMID 41329234, 2025). "The decreased bioavailability of NO, and consequently reduced sGC activity, cGMP levels, and PKG activity, are responsible for the phosphorylation deficit of titin observed in a majority of heart diseases." (PMID 40361188, 2025). "Lastly, we discuss the potential therapeutic approaches for the treatment of heart diseases by targeting titin." (PMID 38660537, 2024).
heart disease (continued). "In this context, similarities in the expression patterns of myosin heavy and light chains, actin, Troponin and Titin during fetal cardiac development and cardiac disease have been summarized previously." (PMID 36909327, 2023). "In this review, we summarize the functional evidences of the role of RBM20 in the regulation of TTN and additional genes involved in heart function and cardiac diseases development." (PMID 32276354, 2020). "The giant protein titin is a central player in cardiac muscle relaxation and contributes to impaired relaxation in cardiac disease." (PMID 31314138, 2019). "Changes in titin isoform composition and phosphorylation occur during development of cardiac disease, which contribute to altered cardiac performance." (PMID 31314138, 2019). "The functional net effect of these changes in phosphorylation appears to be an increase in titin‐based passive tension in heart disease." (PMID 30989819, 2019). "Changes in titin phosphorylation have been investigated in animal models of heart disease and in failing hearts of human patients, usually in comparison to healthy/nonfailing hearts." (PMID 30989819, 2019). "In general, findings on these animal model studies support the concept that decreased phosphorylation of the N2Bus titin segment contributes to the increased myocardial stiffness frequently seen in heart disease." (PMID 30989819, 2019). "Since it is known that RBM20 mainly regulates titin alternative splicing, future work can focus on developing therapeutic agents targeting RBM20 to shift titin isoform in heart disease." (PMID 29304022, 2018). "Even though the precise role of RBM20 in the hormone-induced change in titin splicing is still not clear, these findings provide novel insights into developing therapeutic agents targeting RBM20 to induce titin isoform switching for treatment of heart disease." (PMID 29304022, 2018). "In attempts to overcome this limitation, the phospho-specific antibodies generated against N2Bus and PEVK phosphosites have been used to obtain more detailed information on the phosphorylation status of the unique spring elements of titin in heart disease." (PMID 28510118, 2017). "Variable isoform expression and TTN splicing have become of great importance in different cardiac diseases, including DCM, whereby the compliant N2BA isoform is upregulated and is associated with decreasing passive stiffness and increasing chamber compliance." (PMID 27493940, 2016). "Comprehensive genotype–phenotype studies in families suffering with cardiac disease are necessary to clarify the clinical role of these VUS in the TTN gene." (PMID 26516846, 2015). "For four of these loci, the top gene according to OPEN had been shown to be mutated in DCM (PLN, ACTN2, TNNT2, TTN), while for two others, the top gene was known to be mutated in HCM (MYL2) or an arrhythmogenic form of cardiac disease (CASQ2)." (PMID 25633252, 2014). "It is clear that titin-isoform switching adjusts myocardial passive stiffness, but how the higher or lower proportions of titin isoforms relates to heart disease remains to be characterized." (PMID 24367651, 2013). "Moreover, the variability in isoform expression and TTN splicing is critically important in a range of cardiac diseases." (PMID 41190030, 2025). "Instead, due to the large size of the gene, Titin non truncating variants (TTNntv) are frequently found in the population and are not usually linked to the development of cardiac disease." (PMID 41329234, 2025). "Since the role of TTN missense variants in cardiac disease is still under debate, we assessed the yield of genetic testing without inclusion of TTN missense variants." (PMID 38689299, 2024). "Mis-splicing of titin mitigated by RBM20 was markedly involved in heart diseases." (PMID 35783855, 2022). "The elastic properties of cardiac titin change dynamically during cardiac development and may also be pathologically altered during the course of cardiac disease." (PMID 35846001, 2022).
heart disease (continued). "Different titin isoforms ratio was shown to affect cardiac phenotypes and heart diseases." (PMID 35783855, 2022). "In summary, studies on animal models of heart disease suggest an overall decrease in titin phosphorylation compared to healthy control hearts, which may be driven by hypophosphorylation of residues in the N2Bus segment." (PMID 30989819, 2019). "Titin phosphorylation and isoform shifts have shown alterations with cardiac disease; adjustments in athletes may partly explain divergent athlete–control differences in LV twist mechanics." (PMID 27889869, 2017). "Different kinases can modify the TTN elasticity in different ways; indeed, it is known that changes in post-translational modification (in particular hypophosphorylation) plays a role in the pathophysiology of heart disease." (PMID 27493940, 2016). "Among these 4 genes, TTN was the most likely cardiac disease associated gene while lack of evidence for NPHP3, DNAI1, and MUC5B genes existed." (PMID 28018021, 2016). "However, oxidative changes in titin have the potential to serve as biomarkers and become useful drug targets in specific forms of muscle/heart disease." (PMID 25373878, 2015). "Nonetheless, taking all of our results together, we find it a highly plausible explanation that a superimposed deficiency in expression of the Cronos protein product would result in the more severe forms of human cardiac disease seen in DCM patients with C-terminal TTN truncations." (PMID 26473617, 2015). "In addition to full-length titin molecules, smaller isoforms such as Cronos and Novex 1–3 have recently been identified: to date, their role is still under investigation, both in developmental processes and in pathogenesis of cardiac disease." (PMID 41329234, 2025). "Due to titin’s myriad functional roles in the heart, it is not surprising that disruption of these functions by things such as mutations is associated with the development of heart diseases." (PMID 38660537, 2024). "Although it may be advantageous to modulate Rbm20-dependent titin splicing to decrease passive stiffness in certain types of heart disease where passive stiffness is increased, the effect on other Rbm20 targets such as calcium handling genes must be carefully evaluated." (PMID 30051286, 2018). "As effective regulators of cardiac stiffness based on titin, RBM20 provides novel strategies to treat heart diseases with impaired cardiac compliance, especially HFpEF." (PMID 35783855, 2022). "Furthermore, the relevance of titin oxidation in heart disease is largely unknown." (PMID 30989819, 2019). "Notably, truncating variants in genes such as TTN, FLNC, DSP, PKP2, and MYH7 were frequently reported, particularly in young decedents with no significant history of cardiac disease." (PMID 41374444, 2025). "In this work, we set to answer the question of whether single mSNPs in titin can generically and without the contribution of additional genetic factors lead to cardiac disease." (PMID 27683155, 2016). "MYBPC3, TTN and SCN5A are established cardiac disease genes, but SH3BGR and HMCN2 are not." (PMID 31641117, 2019).
infection (12 papers, 2012 to 2025). The state of being infected such as from the introduction of a foreign agent such as serum, vaccine, antigenic substance or organism. "DCM involves structural and functional impairments of the myocardium, often linked to genetic mutations (e.g., in titin (TTN) and lamin) or acquired factors, including infection, alcohol, drugs, and endocrine disorders." (PMID 41356298, 2025). "The infection progressed over time, resulting in destruction of the 3D TESM structure, as marked by the loss of titin+ skeletal muscle cells at 7 dpi." (PMID 40912913, 2025). "Seven days after infection, myocardial inflammation, remodeling, and titin expression and phosphorylation were examined by immunohistochemistry, real-time PCR and Pro-Q diamond stain." (PMID 28800592, 2017). "The interactions involving Bg-fibronectin, Sm-roundabout 2 and titin are sustained into the infection stage with sporocyst." (PMID 28578678, 2017). "Notable genes in the resistant phenotype included the protein tyrosine kinase src and protein kinase D, with 14-3-3 protein, G-protein coupled receptor kinase 2, twitchin, titin and nuclear factor κB (NFκB) inhibitor differentially expressed only following infection." (PMID 23300533, 2012). "We collected immune sera of infected (with and without treatment) rats during the acute and chronic stages of infection and disease development, and utilized them to determine the levels of anti-titin antibodies by an ELISA that used recombinant and oxidized titin as antigens." (PMID 22238578, 2012). "Interestingly, we have identified elevated serum levels of NEB, VTN, and TTN in SVM patients, while in non-severe infection, serum levels of these candidates were found to be nearly similar compared to the healthy controls." (PMID 27090372, 2016).
cardiovascular diseases (10 papers, 2022 to 2025). "The current study on titin levels in cats and their association with echocardiographic parameters represents an important step forward in our understanding of cardiovascular diseases in cats." (PMID 39619937, 2024). "Moreover, our data provide proof‐of‐concept evidence that targeting titin‐based VSMC tone through the RBM20‐titin axis may be beneficial for the treatment of cardiovascular diseases caused by or involving increased peripheral vascular resistance." (PMID 40119572, 2025). "Genomic test identified variants of uncertain significance in the TTN, MYH11, and RAF1 genes, which are associated with cardiovascular diseases but not directly linked to AF." (PMID 40625395, 2025). "As the largest known protein in the human body, TTN has a crucial, yet not entirely understood, role in cardiac physiology and the pathogenesis of cardiovascular diseases." (PMID 41190030, 2025).
neuromuscular disease (7 papers, 2020 to 2025). "As a first-tier strategy, we recommend comprehensive gene-panel analysis of all neuromuscular disease-related genes, including those commonly implicated in these diseases (e.g., TTN and RYR1)." (PMID 35628876, 2022).
genetic diseases (5 papers, 2018 to 2025). "Mutations in the Ttn gene can result in titinopathies, inherited diseases of cardiac and skeletal muscle, and most of the disease-associated variants involve mutations resulting in significant changes to the expressed titin protein." (PMID 39737810, 2025). "The ttn. gene encodes the titin protein, which is involved in muscle development and has been linked to muscle‐specific genetic diseases among zebrafish (Danio rerio)." (PMID 40958838, 2025). "In recent years, next-generation sequencing (NGS) has discovered many new TTN mutations and gradually recognized TTN as an important gene in human genetic diseases." (PMID 38381767, 2024). "Titinopathies, inherited diseases caused by mutations in the titin (TTN) gene, are responsible for diverse cardiac and muscle diseases." (PMID 30275509, 2018).
inflammation (3 papers, 2020 to 2025). Aberrant reaction of the microcirculation characterized by movement of fluid and leukocytes from the blood into extravascular tissues. "In summary, our results show that systemic inflammation induced by collagen inoculation, contributes to microvascular endothelial inflammation and reduced sGC expression, possibly disrupting the NO-sGC-cGMP signaling pathway that increases titin phosphorylation." (PMID 36494772, 2022). "This pro-inflammatory state leads to coronary microvascular endothelial inflammation, reduced NO bioavailability, diminished protein kinase G (PKG) activity, and titin hypophosphorylation." (PMID 41295261, 2025).
retinopathy (3 papers, 2020 to 2024). "Interestingly, despite that experts in the consortium have ruled out TTN as a causative gene for retinal disorders, the reason why Phenogenon associated TTN with Abnormality of the anterior segment of the globe remains unclear." (PMID 32271766, 2020).
adenocarcinoma (2 papers, 2022 to 2023). A common cancer characterized by the presence of malignant glandular cells.
metabolic disease (2 papers, 2022 to 2025). A congenital disorder (due to inherited enzyme abnormality) or acquired (due to failure of a metabolically important organ) disorder resulting from an abnormal metabolic process. "In terms of drug resistance, TTN mutations are associated with insulin tolerance in metabolic disease and the degree of anthracycline-induced myocardial damage." (PMID 35733807, 2022).
neurodegenerative disease (2 papers, 2024 to 2025). A disorder of the central nervous system characterized by gradual and progressive loss of neural tissue and neurologic function. "Forms of titin have also been identified in neurones in the central and peripheral nervous systems, localised to the nucleolus at the site of ribosomal RNA biogenesis, with implicated roles in neurodegenerative disease." (PMID 41488750, 2025). "Within these neurons, titin localizes to the dense fibrillar component of the nucleolus, the site of ribosomal RNA biogenesis and modification, and a critical site of dysfunction in neurodegenerative disease." (PMID 38496572, 2024).
hematologic malignancies (1 paper, 2025).
mitochondrial disease (1 paper, 2023). "Defects in sarcomere genes, such as MYH7, MYBPC3, TNNT2, TPM1, ACTC1, and TTN have been reported as causative for LVNC and LVNC is also commonly associated with mitochondrial diseases." (PMID 37186429, 2023).
muscular disorder (1 paper, 2016). "However, although a mutation in titin disrupting nbr1 interactions with the kinase domain of titin is associated with a muscular disorder, there are no specific models of NBR1 disruption with an overt muscle phenotype." (PMID 27484057, 2016).
musculoskeletal disease (1 paper, 2026). "A main driving force in the field is to exploit the accumulated knowledge on titin to find new avenues for therapeutic intervention in cardiac and musculoskeletal disease." (PMID 41909620, 2026).
neurodevelopmental disorder (1 paper, 2022). A behavioral and cognitive disorder with onset during the developmental period that involves impaired or aberrant development of intellectual, motor, or social functions. "Considering the miRNA and piRNA target genes common to multiple samples, four were already present in SFARI database: NACC1, SMAD4, TNRC6B, and TTN, and their mutants are implicated in ASD and other neurodevelopmental disorders." (PMID 35405953, 2022).
TTN also shares sentences with these, for which no sentence is quoted: cardiac arrhythmias (8 papers); familial hypertrophic cardiomyopathy (6); Becker muscular dystrophy (5); peripartum cardiomyopathy (5); familial hypercholesterolemia (4); acute myocardial infarction (3); catecholaminergic polymorphic ventricular tachycardia (3); colon adenocarcinoma (3); colorectal adenocarcinoma (3); encephalitis (3); fatal cardiomyopathy (3); limb girdle muscular dystrophy type 2J (3); long QT syndrome (3); myasthenia (3); thalassemia (3); alcoholism (2); autosomal dominant distal myopathy (2); connective tissue disorder (2); dystroglycanopathies (2); endocrine disorders (2); epilepsy (2); hereditary myopathy with early respiratory failure (2); Hodgkins lymphoma (2); idiopathic dilated cardiomyopathy (2); kidney disease (2); left ventricular noncompaction cardiomyopathies (2); long QT syndrome 3 (2); malnutrition (2); Marfan syndrome (2); mdm (2).
A further 141 diseases each share a sentence with TTN in 2 papers or fewer.